SIRPA (signal regulatory protein alpha)
Diseases named in the same sentence as SIRPA in open-access papers (continued):
Sharing a sentence is not in itself a finding about the gene and the disease.
tumor (continued). "Signal-regulatory protein α (SIRPα) is a myeloid leukocyte-expressed inhibitory regulator whose canonical function is to inhibit professional phagocytes (mainly macrophages) from phagocytosing self-cells including tumor cells via interacting with the self-recognition marker CD4710." (PMID 34050181, 2021). "While therapies targeting SIRPα do not cause direct cytotoxicity on tumor cells, CD47-targeting therapies may induce phagocytosis and direct cytotoxicity of CD47+ cancer cells by engaging activating Fcγ receptors on macrophages and NK cells." (PMID 34572013, 2021). "Given that robust proliferation and activation of antitumor Tc is integral to tumor eradication induced by Sirpα−/− macrophages and local RT, implementing PD-L1 blockade into this combination may significantly enhance the efficacy of Sirpα−/− macrophage-based antitumor treatments." (PMID 34050181, 2021). "Interestingly, cell subpopulation analysis of CD45+ leukocytes showed that intratumoral Sirpα−/− macrophages rapidly disappeared after IR, occurring prior to detectable tumor regression, whereas endogenous WT (Sirpα+) macrophages in WT mice did not reduce in number." (PMID 34050181, 2021). "CD47 binds to a myeloid and neuronal cell receptor called signal regulatory protein α (SIRPα), which initiates a signaling cascade within the bound phagocyte via immunoreceptor tyrosine-based inhibition motifs to inhibit immunoglobulin- or complement-induced efferocytosis of the tumor cell." (PMID 35582455, 2020). "However, the profile and regulatory mechanism of Sirpα expression in tumor-associated macrophages (TAMs) are still not clear." (PMID 32296015, 2020). "There is growing evidence that the CD47/SIRPα axis may inhibit phagocytosis of tumor cells." (PMID 33552071, 2020). "Interestingly, vaccination with CD47-deficient tumor cells induced a significantly increased expansion and activation of CD11c+SIRPα+ (F4/80−CD64−) DCs, but not of F4/80+CD64+ monocytes/macrophages." (PMID 31996683, 2020). "Also, macrophages recognize pro-phagocytic signals, such as calreticulin and phosphatidylserine that are induced on tumor cells as a result of therapies such as chemotherapy and radiotherapy, which in combination with inhibition of the SIRPα/CD47 axis are shown to promote tumor cell uptake." (PMID 31801627, 2019). "The CD47/SIRPα axis has been targeted with anti-CD47 blocking antibodies and non-functional engineered SIRPα variants, in combination with anti-tumor therapeutic antibodies such as Rituximab, Cetuximab, and Trastuzumab, displaying synergistic activity in augmenting macrophage phagocytosis." (PMID 31067629, 2019). "In addition, recombinant CD47 proteins blocking the interaction between CD47 and SIRPα may also contribute to the elimination of tumor cells." (PMID 31921125, 2019). "Furthermore, when activated human dendritic cells or macrophages were co-cultured with CD47 positive human tumor cells, SIRPα - Fc-CD40L was shown to enhance phagocytosis of human tumor cells, and in vivo in mice, induced rapid activation of CD4+ and CD8+ dendritic cells." (PMID 30400822, 2018). "Tumor-targeting antibodies may be conjugated with anti-CD47 or SIRPα-Ig to increase specificity." (PMID 28077173, 2017). "In addition, CD47:SIRPα interaction may also indirectly promote tumor dissemination through binding of tumor cells to macrophages that reside at the level of potential extravasation sites within the vascular wall." (PMID 26578962, 2015). "SIRPα could also target paxillin and cofilin while inhibiting phagocytosis which is mediated by additional phagocytic receptors such as FcγR and during the phagocytosis of particles other than myelin-debris such as aging red blood cells and tumor cells." (PMID 24795566, 2014). "Thus, if thymic Sirpα+ cDCs can be well tuned, the secretory tumor-specific antigens may become more beneficial for the immune surveillance against a tumor." (PMID 22815949, 2012).
tumor (continued). "[64Cu]Cu-SIRPα-Nb PET uptake increased in human SIRPα or human CD47 knock-in mice in various myeloid cell–enriched organs, such as the spleen, the tumor, and the salivary glands, compared with the uptake in wild-type animals or a nonspecific control tracer." (PMID 40876955, 2026). "SIRPα, an inhibitory receptor highly expressed on myeloid cells, binds to CD47, a "don't eat me" signal expressed on tumor cells, to inhibit phagocytosis and enable immune evasion." (PMID 41486149, 2026). "Therapeutically, SIRPα blockade promotes pro-inflammatory polarization of TAMs and DCs, boosts CD8+ T cell-mediated immunity, and suppresses tumor progression in preclinical models." (PMID 41486149, 2026). "Recent research indicates that silencing SIRPα in CAR-Ms markedly enhances phagocytosis and cytotoxicity against HER2-positive tumours, leading to reduced tumour growth and increased survival in mouse models." (PMID 41559435, 2026). "Immunohistochemical testing determined SIRPα expression in peritumoral immune infiltrates and CD47 expression in tumor and immune cells, while tumor proportion score (TPS) and combined positive score (CPS) were used to evaluate CD47 staining." (PMID 40926176, 2026). "Further studies should examine the expressions of CD47 and CD24 at the transcriptional levels to further understand the mechanism of CD47/SIRPα and CD24/Siglec‐1 pathways in the anti‐tumor immune response." (PMID 41354057, 2025). "Using IF analysis, we found anti-SIRPα treatment significantly upregulated infiltration and GZMB expression of CD8+ T cells in these tumor tissues." (PMID 40523887, 2025). "Tumor cells overexpress anti-phagocytic molecules such as the glycoprotein CD47, which engages SIRPα (Signal Regulatory Protein Alpha) on macrophages to inhibit phagocytic uptake and cytoskeletal rearrangement." (PMID 41373540, 2025). "Nanoparticles coated with CD47 can interact with SIRPα on macrophages to avoid clearance, while those designed to block CD47–SIRPα interactions can promote the phagocytosis of tumor cells by inhibiting this signaling pathway." (PMID 40801742, 2025). "We show tumor-specific binding and CD47 blocking by the SIRPα-αMSLN LicMAb even in the presence of healthy CD47-expressing cells." (PMID 40402266, 2025). "The "don't eat me" signaling pathway, mediated by the SIRPα/CD47 axis, has gained substantial attention for its role in regulating macrophage phagocytosis and enabling tumor immune evasion." (PMID 40208335, 2025). "As was observed in vitro, NDV infection led to an increase in the number of GFP+ CD47+, CD45+ SIRPα+, and CRT+ GFP+ tumor cells." (PMID 41322194, 2025). "Tumor cells frequently overexpress CD47, a “Don’t Eat Me” signal that binds to SIRPα on macrophages, inhibiting phagocytosis." (PMID 39982231, 2025). "Blocking the interaction of CD47 with SIRPα reduces Src homology region 2 domain-containing phosphatase 1 (SHP-1) and SHP-2 activation, restoring the anti-tumor activities of APCs." (PMID 41322194, 2025). "In conclusion, the SIRPα mutant engineered by oAd-SA has demonstrated remarkable efficacy, achieving a substantial reduction in CD47 expression across a variety of mouse tumor cell lines." (PMID 40070841, 2025). "Depletion of CD47 has been shown to restore macrophage-mediated phagocytosis of tumor cells and suppress GBM growth, highlighting the therapeutic potential of targeting the CD47/SIRPα axis." (PMID 40800581, 2025). "In tumor cells, CD47 is frequently overexpressed and binds to the inhibitory receptor SIRPα, primarily expressed on myeloid cells, thus facilitating innate immune escape." (PMID 41514569, 2025). "The dual-blocking mechanism effectively neutralized the “don’t eat me” signal by simultaneously targeting SIRPα on macrophages and CD47 on tumor cells, thereby circumventing tumor immune evasion." (PMID 40948940, 2025).
tumor (continued). "OAds expressing TIM-3, 4-1BBL, (SIRPα)-IgG1 Fc, ICOSL, CD40L, and OX40L demonstrated antitumor effects across various preclinical tumor models." (PMID 40698086, 2025). "This engineered nano-bioconjugate system achieved tumor targeting through specific CD47 recognition and facilitated controlled release of anti-SIRPα and anti-CD47 antibodies within the acidic TME." (PMID 40948940, 2025). "Simultaneously, it has the potential to block the SIRPα-mediated non-CD47-dependent pathway, reprogramming the suppressive tumor immune microenvironment." (PMID 40589735, 2025). "The CD47-SIRPa axis promotes immune evasion in HCC and a cold HCC phenotype since overexpression of CD47 allows HCC tumor cells to transmit inhibitory signals upon binding with SIRPa." (PMID 41012682, 2025). "Tumor cells frequently evade macrophage-mediated phagocytosis by expressing CD47-binding peptides (CD47), which binds to SIRPα on macrophages." (PMID 40317075, 2025). "Combining CD47/SIRPα-targeted treatments with other therapeutic modalities, including angiogenesis inhibitors and ICIS, can further suppress tumor progression." (PMID 40607438, 2025). "Overexpressed on tumor cells, CD47 binds SIRPα on macrophages, leading to phosphorylation of immunoreceptor tyrosine-based inhibitory motifs (ITIMs) and inhibiting phagocytosis." (PMID 40079009, 2025). "BI 765063 prevents ligand binding between SIRPα and CD47 by binding to SIRPα, thereby blocking cellular signaling that would lead to a decrease in anti-tumor substances (e.g., macrophages and DCs) in myeloid cells." (PMID 40356928, 2025). "Competitive binding of anti-CD47 antibodies to CD47 on tumor cells blocks the interaction between CD47 and SIRPα on CAR-Ms, thereby reversing macrophage immune suppression and significantly enhancing the phagocytic activity of CAR-Ms." (PMID 40814015, 2025). "Many tumor cells express high levels of CD47, which binds to its ligand, SIRPα (signal regulatory protein alpha), inhibiting macrophage-mediated phagocytosis." (PMID 40012016, 2025). "In both WT and SIRPα−/− mice, the rate of tumor growth depends on the number of engrafted MC38 cells: A higher number of cells leads to more rapid tumor growth." (PMID 41296731, 2025). "Tumor-derived EVs also express CD47, a protein found on tumor cells that normally binds to signal regulatory protein alpha (SIRPα) on macrophages to inhibit phagocytosis." (PMID 40006624, 2025). "NDV has yet to be evaluated in combination with an ICI that targets a tumor:innate immune signaling pathway, such as CD47:SIRPα." (PMID 41322194, 2025). "Additionally, tumor-intrinsic SIRPα may facilitate tumor growth and immune evasion." (PMID 40589735, 2025). "In our study, we found that SIRPα blockade therapy inhibited PI3K/AKT signaling in myeloid cells to suppress the PD-L1 expression and polarization of TIMs to pro-tumor M2-like TAMs or G-MDSCs." (PMID 40523887, 2025). "Engineered exosomes expressing SIRPα, PD-1, and LILRB1 interact with receptors on tumor cells (CD47, PD-L1, and B2M), promoting the phagocytosis of tumor cells and enhancing antigen presentation by immune cells." (PMID 39465690, 2025). "Often overexpressed on tumor cells, CD47 interacts with SIRPα on macrophages (a trans interaction) to deliver a “don’t eat me” signal, allowing for tumor cells to evade immune detection." (PMID 40725081, 2025). "Tumor cells frequently overexpress CD47, which, upon binding to SIRPα on the surface of macrophages, transmits a “don't eat me” signal." (PMID 40607254, 2025). "Next, using Ad1, Ad2, and φm values from i.v. injection experiments, we predict the tumor response when WT mice receive intratumoral (i.t.)injection of WT (SIRPα+ bone marrow–derived macrophages (BMDM), and SIRPα− macrophages, in conjunction with RT at 8 Gy." (PMID 41296731, 2025). "Using flow cytometry, we detected HCC tissues from 12 patients, and found that SIRPα was upregulated in CD45+ immune cells compared with that in liver and para-tumor tissues." (PMID 40523887, 2025).
tumor (continued). "SIRPα inhibits macrophage phagocytosis by interacting with its ligand, CD47, a key immunosuppressive signaling molecule involved in the immune escape of tumor cells." (PMID 40356928, 2025). "SIRPA blockade also rescued the numbers of CD8+ T cells and NKP46+ NK cells in tumour-bearing livers of Clec4fcreId3f/f mice, the formation of the peritumoural CD8+ T cell and NKP46+ NK-rich zone and the production of IFNγ and TNF by CD8+ T cells and NK cells." (PMID 38326607, 2024). "CD47 is a ligand expressed in many tumor cell types, and by binding with the macrophage receptor CD47-signal regulatory protein alpha (SIRPα), it can regulate the phagocytic activity of macrophages." (PMID 38730724, 2024). "CD47 is an extracellular ligand of SIRPα, and the combination of SIRPα and CD47 reduces the phagocytic activity of macrophages by producing inhibitory signals, resulting in tumor immune escape." (PMID 38560565, 2024). "Blockade of CD47/SIRPα and CD24/Siglec-10 pathways can promote macrophage-mediated phagocytosis of tumor cells." (PMID 38971872, 2024). "Innate immune checkpoints, such as the CD47/SIRPα axis, PD-1/PD-L1 axis, and MHC-I/LILRB1 axis, play important roles in tumor-mediated immune escape from the clearance by phagocytosis." (PMID 38383737, 2024). "In a similar manner to the in vivo tumor setting, TCM-treated M-MDSCs, which were the dominant cell type in these cultures, showed increased expression of PD-L1, ARG1, and SIRPα." (PMID 38577107, 2024). "Tumor cells evade phagocytosis by overexpressing “don’t eat me signals”, such as CD47 and CD24, which interact with their binding partners SIRPα and SIGLEC10, respectively, that are abundantly expressed on innate immune cells." (PMID 38459166, 2024). "CD47 is a transmembrane protein with a well-described role as a “don’t eat me” signal due to its binding to signal regulatory protein a (SIRPa) on myeloid cells and high CD47 expression on tumor cells is thought to protect tumor cells from immune responses." (PMID 39281684, 2024). "Myeloid cells, including macrophages, express signal regulatory protein alpha (SIRPα), a receptor that recognizes CD47 and, when binds to it, provides a down-regulatory signal preventing the phagocytosis of tumor cells." (PMID 39003350, 2024). "Here, we explored the role of the tumor microenvironment in regulating MDSC differentiation and immunosuppressive properties via signal-regulatory protein alpha (SIRPα)/CD47 signaling." (PMID 38577107, 2024). "The results depicted demonstrate that the combination of SIRPα-Fc and VEGFR1-Fc resulted in the complete suppression of tumor growth in the Hu-PDX1 model." (PMID 38532108, 2024). "The selective targeting of tumor cells by anti-CD47 antibodies is based on the interaction between CD47, often overexpressed on cancer cells, and signal regulatory protein alpha (SIRPα) on phagocytic cells." (PMID 39682299, 2024). "Tumor cells typically overexpress CD47, triggering the inhibitory receptor SIRPα expressed on macrophages to evade phagocytosis and antitumor immunity." (PMID 39697556, 2024). "In preclinical tumor-bearing mouse models, simultaneous blockade of CD47/SIRPα and PD-1/PD-L1 further inhibits tumor growth." (PMID 38462636, 2024). "Tumor cell surface molecule CD47 binds to its ligand, the signal regulatory protein α (SIRPα) on the macrophage cell surface, and provides a safety signal, blocking phagocytosis." (PMID 39660126, 2024). "Some tumor cells exhibit CD47 and/or SIRPα overexpression, utilizing the “don't eat me” signaling to evade immune response and facilitate tumor invasion." (PMID 39240588, 2024). "As an important tumor antigen that affects the onset and progression of various cancers, CD47 interacts with SIRPα to release a certain signal to escape phagocytosis." (PMID 39169402, 2024).
tumor (continued). "In addition, it has been reported that CD47/SIRPA blockade with either SIRPα variants acting as an analogue of anti-CD47 antibody or anti-SIRPA antibody does not effectively induce phagocytosis on its own and requires additional tumor-opsonizing antibodies to be efficacious." (PMID 38920727, 2024). "The bispecific fusion protein SIRPα-VEGFR1 was employed to concurrently target CD47 and VEGF, resulting in significant suppression of tumor growth in the Hu-PDX model." (PMID 38532108, 2024). "Genetically modified SIRPa-Fc can block CD47, and these can therefore be delivered by OVs to hone an immune response toward tumor cells by macrophages exerting a therapeutic benefit." (PMID 38533720, 2024). "Tumor cells upregulate CD47 expression to evade phagocytosis, with CD47 acting as a ligand for three different receptors: signal regulatory protein alpha (SIRPα), thrombospondin-1 (TSP-1), and integrins, including αvβ3 and α2β1." (PMID 38785789, 2024). "TTI-621, a SIRPα-hIgG1 Fc fusion protein, selectively promotes macrophage-mediated phagocytosis by binding to CD47 on tumor cells." (PMID 38783333, 2024). "Blocking CD47 with monoclonal antibodies or soluble SIRPα-Fc can trigger macrophage-mediated ADCP and significantly kill tumor cells." (PMID 39379603, 2024). "IMM01, a recombinant human SIRPα fusion protein, can bind to CD47 on the tumor cell membrane to mediate macrophage phagocytosis of tumor cells." (PMID 38464520, 2024). "Based on the current paradigm, disruption of the CD47-SIRPA interaction by either anti-CD47 or anti-SIRPA antibody would inhibit the “don’t eat me” signal and thus promote tumor phagocytosis." (PMID 38920727, 2024). "Blocking CD47 signaling with an oncolytic adenovirus carrying a SIRPα-IgG1Fc fusion gene (SG635-SF) significantly increases macrophage infiltration into the tumor and suppresses tumor growth in OC mice." (PMID 39513610, 2024). "Tumor cells often evade the innate immune system by expressing CD47, a ‘do not eat me’ signal that inhibits phagocytosis when it binds to SIRPα on macrophages, thereby promoting tumor invasion." (PMID 38543204, 2024). "To investigate the spatial connection of SPP1 + SIRPα + macrophages with tumor cells and CD8 + T cells, we conducted in-situ mIHC staining in 39 ESCC patients from ESCC cohort 1 using antibodies against CD68, SIRPα, SPP1, panCK, PD-1, and CD8." (PMID 39696410, 2024). "The in vivo anti-tumor activity of NILK-2401 was investigated in a mouse xenograft model, using SNU-C1 as target cells, as well as in a syngeneic model using human SIRPα/human CD47 transgenic mice with MC38 transfected with human CEACAM5 and human CD47." (PMID 38720892, 2024). "The mouse anti-SIRPα antibody clone P84 has been reported to have little effect on the CD47/SIRPα interaction, and its ability to decrease tumor growth seems dependent on tumor type and treatment schedule." (PMID 38414061, 2024). "Below, we report the findings of studies identified using the PubMed search “lung AND (cancer OR tumor OR tumour) and (CD47 or SIRPα)”." (PMID 37958404, 2023). "Blockade of the CD47/SIRPa pathway can enhance macrophage-mediated phagocytosis (MMP), increase the frequency of TAMs in TME, and reduce tumor growth." (PMID 36761751, 2023). "Currently, by blocking CD47-signal regulatory protein α (SIRPα) signaling, restoring phagocytosis of tumor cells by macrophages, and promoting the response of effector CD8+ T cells, tumor cell proliferation and metastasis are effectively inhibited." (PMID 37055849, 2023). "Signal regulatory protein alpha (SIRPα) is a receptor expressed on macrophages that can interact with CD47, which is upregulated on some tumor cells, and thus transmit a “don’t eat me” signal." (PMID 36960057, 2023). "There are multifactorial potential interactions between T-ALL and stroma that shape the myeloid anti-tumor immune response, including between CD47/SIRPα, PD-L1/PD-1, CD40/CD40L, and CD28/CD80/86." (PMID 36897988, 2023).